PTGER2 (prostaglandin E receptor 2)
Description:
Receptor for prostaglandin E2 (PGE2). The activity of this receptor is mediated by G(s) proteins that stimulate adenylate cyclase. The subsequent raise in intracellular cAMP is responsible for the relaxing effect of this receptor on smooth muscle.
Synonyms: EP2; COX-2
Tractability: Small molecule: an approved drug acts on it; a structure with a bound ligand is known; a high-quality ligand is known; it belongs to a druggable protein family. Antibody: its Gene Ontology location is reachable by antibodies, with high confidence; UniProt places it where antibodies can reach, with medium confidence; UniProt predicts a signal peptide or a membrane-spanning region. PROTAC: a small molecule that binds it is known.
Target class: Lipid-like ligand receptor (family A GPCR); Membrane receptor; Prostanoid receptor; Small molecule receptor (family A GPCR); Family A G protein-coupled receptor
Chemical probes: CHEMBL3586360, ONO-8815Ly, PD082297, PF-04418948 (high quality)
Safety:
Unwanted effects reported when the protein is acted on. In parentheses: how it was acted on, where the effect was seen, and who reports it.
decreased uterine motility (activation, acute dosing; urogenital, immune; source: Lynch et al. (2017))
decreased/increased inflammation (inhibition, acute dosing; urogenital, immune; source: Lynch et al. (2017))
increased/decreased inflammation (activation, acute dosing; urogenital, immune; source: Lynch et al. (2017))
aspirin-intolerant asthma (source: ClinPGx)
Gene: Protein-coding gene on chromosome 14 (52,314,305 to 52,329,822, forward strand). Ensembl gene ENSG00000125384.
Subcellular location: Cell membrane
Pathways (Reactome):
Signal Transduction: G alpha (s) signalling events; Prostanoid ligand receptors
Gene Ontology:
Molecular function: prostaglandin E receptor activity; G protein-coupled receptor activity
Biological process: adenylate cyclase-activating G protein-coupled receptor signaling pathway; cellular response to prostaglandin E stimulus; G protein-coupled receptor signaling pathway; inflammatory response; positive regulation of cytosolic calcium ion concentration; response to progesterone
Cellular component: plasma membrane; membrane
Genetic constraint (gnomAD): Loss-of-function variants: 22 observed, 25.31 expected, observed/expected ratio (o/e) 0.87, 90% interval 0.62 to 1.24. The upper end of that interval is the gene's LOEUF score, 1.24, which puts it in group 5 of 6, group 1 being the genes least tolerant of losing a copy. Missense variants: 458 observed, 485.11 expected, observed/expected ratio (o/e) 0.94, 90% interval 0.87 to 1.02. Synonymous variants: 219 observed, 207.46 expected, observed/expected ratio (o/e) 1.06, 90% interval 0.94 to 1.18.
Homologues: Orthologues: chimpanzee PTGER2 (99% identical), macaque PTGER2 (98% identical), rabbit PTGER2 (91% identical), dog PTGER2 (88% identical), mouse Ptger2 (87% identical), pig PTGER2 (85% identical), rat Ptger2 (84% identical), guinea pig PTGER2 (84% identical), tropical clawed frog ptger2 (53% identical), zebrafish ptger2b (42% identical), zebrafish ptger2a (41% identical). Paralogues in human: PTGDR (41% identical), PTGIR (39% identical), PTGER4 (33% identical), PTGER1 (27% identical), PTGER3 (25% identical), TBXA2R (23% identical), PTGFR (21% identical).
Diseases named in the same sentence as PTGER2 in open-access papers:
PTGER2 is named in the same sentence as 59 diseases in open-access papers, as found by Europe PMC text mining. Sharing a sentence is not in itself a finding about the gene and the disease. The quoted sentences say what the papers report.
asthma (7 papers, 2012 to 2024). "Genetic studies have also suggested that polymorphisms in the PTGER2 gene (which encodes PGE2 receptor EP2) are specifically associated with aspirin‐intolerant asthma." (PMID 36181709, 2023). "A Korean study showed the promoter variant rs207579 (−616C>G) in PTGER2 to be associated with increased asthma risk whereas two variants in the 3′-UTR of PTGER3 (rs959 and rs34745168) were associated with a diminished risk." (PMID 27708579, 2016). "Polymorphisms in its receptor PTGER2 were mainly found to be associated with aspirin-intolerant asthma, but in some studies also with asthma in general." (PMID 22432035, 2012). "Indeed, PTGER2 gene polymorphisms are associated with asthma especially NERD and patients with NERD have decreased EP2 expression." (PMID 36181709, 2023). "Moreover, Ptger2-deficient mice, which lack EP2, had exaggerated airway inflammation in an antigen-challenged asthma model." (PMID 39015572, 2024). "The explanation for this phenomenon is, that according to our evaluation, SNPs in the PTGER2 influence asthma susceptibility in interactions or indirectly, and similarly, the association between a SNP in MS4A2 and asthma is transitive, which is hard to detect with traditional frequentist methods." (PMID 22432035, 2012). "Associations were confirmed between SNPs in PTGDR, PTGER2, MS4A2 and asthma." (PMID 22432035, 2012). "In N-ERD vs. asthma comparison, we detected five SNPs in four genes (PPARG, IL10, PTGER2, and OBSCN)." (PMID 31936183, 2020). "We compared the gene expression levels of genes found to be relevant in asthma in the SNP analysis in sputum samples of 12 asthmatics and 9 controls using TaqMan Gene Expression Assays (FRMD6, PTGDR, PTGER2, MS4A2, AHNAK, PRPF19, TXNDC16)." (PMID 22432035, 2012). "Altogether 5 SNPs in 4 genes were found relevant in connection with asthma phenotype: PRPF19 on chromosome 11, and FRMD6, PTGER2 and PTGDR on chromosome 14." (PMID 22432035, 2012). "In the BN-BMLA analysis altogether 5 SNPs in 4 genes were found relevant in connection with asthma phenotype: PRPF19 on chromosome 11, and FRMD6, PTGER2 and PTGDR on chromosome 14." (PMID 22432035, 2012).
colorectal cancer (5 papers, 2011 to 2025). A primary or metastatic malignant neoplasm that affects the colon or rectum. "Mapping the genes in the colorectal cancer metastasis signalling pathway revealed that syntenin-1 downregulation led to downregulation of the membrane proteins Frizzled and PTGER2." (PMID 32595209, 2020). "Moreover, PTGS2 overexpression is an early event in colorectal cancer development, and PTGER2 plays a critical role in PTGS2-induced colon cancer development in an experimental system." (PMID 37601099, 2023). "Both our patients have H3K4me3 on the PTGER2 gene in normal tissue and gained H3K27me3 in the tumor, which offers a mechanistic explanation to the previously reported expression pattern of this gene in colorectal cancer." (PMID 22011431, 2011). "To examine how syntenin-1 affected tumour cell properties in colorectal cancer, we conducted microarray analysis by IPA using SW480 with downregulated syntenin-1, and we found that PTGER2 was suppressed in conjunction with syntenin-1." (PMID 32595209, 2020).
endometriosis (5 papers, 2020 to 2025). The growth of functional endometrial tissue in anatomic sites outside the uterine body. "Elevated Ptger2 expression in the DRG was recently shown in a murine endometriosis model." (PMID 31969159, 2020). "Using machine learning algorithms, five key genes were selected in the endometriosis: BST2, IL4R, INHBA, PTGER2, and MET." (PMID 40405976, 2025). "As a consequence, the therapeutic inhibition of COX-2, PGE2, and/or their receptors—prostaglandin E receptor 2 (PTGER2) and prostaglandin E receptor 4 (PTGER4)—decreases the survival and invasive ability of endometriosis cells." (PMID 37447296, 2023). "Epigenetic alterations of a few genes (DLX5, CDKN1C, PTGER2, and GATA3) are common for endometriosis and obstetric complications." (PMID 34833476, 2021). "Other evidence may strengthen our findings as PTGER2 and PTGER4 were found to play a key role in endometriosis development, and their inhibition leads to poor prognosis." (PMID 41583321, 2025). "A recent study showed that Ptger2 but not Ptger4 expression in DRG escalates in a murine model with endometriosis lesions." (PMID 31969159, 2020).
cervical cancer (4 papers, 2012 to 2024). A primary or metastatic malignant neoplasm involving the cervix. "Increased DNA methylation of PTGER2 is associated with the progression of neuroblastomas, non-small cell lung cancer, and cervical cancer tissue, suggesting that the aberrant methylation of this gene regulates cell proliferation." (PMID 31969157, 2020). "Our laboratory and others have demonstrated elevated expression of PTGS1, PTGS2, the E-series prostanoid receptors PTGER2 and PTGER4 together with enhanced biosynthesis and signaling of PGE2 in cervical carcinomas." (PMID 22442729, 2012). "We have previously shown that PTGS1, PTGS2, PTGER2 and PTGER4 are elevated in cervical cancers." (PMID 22442729, 2012). "PTGER2 expression is a prognostic factor for the overall survival in the subgroup of negative PTGER3, and high galectin-3 expressed cervical cancer patients." (PMID 36010605, 2022). "PTGER2 expression increases while PTGER3 expression decreases during cervical neoplasia development, suggesting these receptors might be considered as positive and negative prognostic markers of cervical cancer lesions, respectively." (PMID 36010605, 2022).
adenoma (3 papers, 2020 to 2022). A neoplasm arising from the epithelium. "SSTR1 was highly upregulated in invasive adenoma (log2FC = 9.14, p = 0.005) as well as the adhesion receptor ADGRG2 (log2FC = 5.26, p = 0.026), the serotonin receptor HTR4 5 (log2FC = 3.68, p = 0.007) and the prostaglandin receptor PTGER2 (log2FC = 3.06, p = 0.038)." (PMID 35203352, 2022).
colon cancer (3 papers, 2017 to 2023). "In conclusion, our present results demonstrated that syntenin-1 is related to the CSC properties of colon cancer cells through regulation of PTGER2." (PMID 32595209, 2020). "Among the PG receptor subtypes examined, genetic deletion of EP2 (Ptger2) specifically and almost completely suppressed colon tumor formation in AOM-DSS model of mice." (PMID 29259703, 2017).
Hypertension (3 papers, 2016 to 2022). The presence of chronic increased pressure in the systemic arterial system. "CYP3A4, APOA2, PPARG, ALOX, and CYP4F2, proteins related to lipid homeostasis affect the occurrence of hypertension, and PTGER2, ALOX5, LTF, ITGB, and GATA3 relate to the inflammatory and immune response in glomeruli." (PMID 30809144, 2019). "As the prostaglandin E2 receptor, activation of PTGER2 accentuates chronic inflammation and protects against angiotensin II-induced hypertension via inhibition of oxidative stress." (PMID 30809144, 2019). "Previous studies indicated that targeted disruption of PTGER2 results in hypertension." (PMID 35933330, 2022).
ovarian carcinoma (3 papers, 2015 to 2025). A malignant neoplasm originating from the surface ovarian epithelium. "m6A modification of prostaglandin E receptor 2 (PTGER2) is upregulated in ovarian cancer; this is associated with self‐renewal and DNA damage repair capabilities in cancer cells leading to resistance to therapy." (PMID 39661414, 2024). "This is reinforced by studies demonstrating that PTGER2 in ovarian cancer is identified as an oncogene that promotes cancer stem cell properties and resistance to chemotherapy, resulting in poor prognosis." (PMID 41583321, 2025). "PTGER2 and PTGER4 have been most studied in ovarian cancer and implicated in promoting growth and pro-tumorigenic cytokine production." (PMID 25972361, 2015).
breast cancer (2 papers, 2019 to 2024). A primary or metastatic malignant neoplasm involving the breast. "Finally, we analyzed the association between IL-6, PTGER2, and PTGER4 overexpression and breast cancer subtype; hormone receptor status; and distant metastasis-free or overall survival." (PMID 31014367, 2019). "Two mammary tumor cell lines, PY8119 and E0771, were similar in terms of the absence of Ptger2 expression but showed quite different levels of Ptger4, with E0771 being almost completely deprived of the receptor expression." (PMID 39298269, 2024).
fibrosis (2 papers, 2019 to 2020). the formation of excess fibrous connective tissue in an organ or tissue in a reparative or reactive process. "In addition to diminished PGE2 production and signaling in fibrotic lungs, fibroblasts from IPF lungs, and mice with experimental fibrosis showed resistance to antifibrotic activities of PGE2 due to decreased expression of EP2 (PTGER2)." (PMID 32549377, 2020). "Then we further analyzed the mRNA and protein expressions of PTGER2 and α-SMA (the fibrotic marker) of cells from control group, fibrosis group and HA-Cur group." (PMID 31616564, 2019).
idiopathic pulmonary fibrosis (2 papers, 2015 to 2019). Idiopathic pulmonary fibrosis (IPF) is a nonneoplastic pulmonary disease that is characterized by the formation of scar tissue within the lungs in the absence of any known cause. "Prostaglandin E receptor 2 expression (PTGER2) has also been linked with pulmonary fibrosis." (PMID 26435749, 2015). "In some fibrotic diseases, such as idiopathic pulmonary fibrosis (IPF), the inhibition of PGE2 expression in myofibroblasts was due to the decreased expression of the prostaglandin E receptor 2 (PTGER2), the major G protein-coupled receptor of PGE2." (PMID 31616564, 2019).
infertile (2 papers, 2009 to 2017). "Therefore, we suggest that downregulation of PTGER2 signaling with aging may lead to infertility or a declining pregnancy rate." (PMID 28806906, 2017).
neuroblastoma (2 papers, 2018 to 2020). Neuroblastoma (NB) is the most common solid, extracranial childhood tumor. "The expression of PTGER2 is often silenced in neuroblastoma cell lines by epigenetic mechanisms." (PMID 31969157, 2020).
anemia (1 paper, 2023). A reduction in the number of red blood cells, the amount of hemoglobin, and/or the volume of packed red blood cells. "FKN induces the secretion of the receptivity-related cytokines at anemia, which may improve endometrium receptivity via the CX3CR1 and the regulation of the NFκB pathway and by regulating activin, follistatin, and BMP2, as well as PR, SOX-17, PTGER2, and TIMP2." (PMID 37175630, 2023).
aortic valve disease (1 paper, 2024). "Additionally, AS from LVH demonstrates upregulated anti-inflammatory COX receptor-related genes PTGER2 and PTGER4, and LOX-derived LT receptor-related gene CYSLTR2, but downregulated TBXAS1 and ALOX5, suggesting different mechanisms causing aortic valve disease and aortic calcification." (PMID 39062733, 2024).
atherosclerosis (1 paper, 2023). A disease characterized by the build-up of fatty material and calcium deposition in the arterial wall resulting in partial or complete occlusion of the arterial lumen. "The chemokine production of human macrophages was suppressed by PGE2 through PTGER2 in the progression of atherosclerosis plaque." (PMID 36978012, 2023).
autoimmune disease (1 paper, 2021). A disorder resulting from loss of function or tissue destruction of an organ or multiple organs, arising from humoral or cellular immune responses of the individual to their own tissue constituents. "Both in humans and mouse models, prostaglandin E receptor 2- (PTGER2-) β-catenin axis serves as a bridge between high-salt diet and autoimmune disease by modulating Treg properties." (PMID 33505215, 2021).
breast tumor (1 paper, 2022). "This can be traced in contrasting pairs such as miR-19a/PTGER2 (pancreatic tumor); miR-421/PTGER2 (uterine tumor); miR-590/PTGFR (uterine and breast tumor); miR-20a/PTGER3 (uterine tumor)." (PMID 35453789, 2022).
endometrial adenocarcinoma (1 paper, 2011). "In addition we have shown that the PTGER2 and PTGFR receptors can crosstalk via the Gs and Gq pathways to enhance cAMP signalling and target gene transcription in endometrial adenocarcinoma cells in vitro." (PMID 21589857, 2011).
gastric tumors (1 paper, 2018). "Among these genes, we further selected six GI hormone receptors whose expression was significantly down-regulated by 80–100% in the primary gastric tumors, including neuropeptide Y receptors (NPY1R and PPYR1), prostanoid receptors (PTGDR, PTGER2, and PTGER3), and a somatostatin receptor (SSTR2)." (PMID 30510283, 2018). "The qRT-PCR and bisulfite sequencing analyses of the six genes (NPY1R, PPYR1, PTGDR, PTGER2, PTGER3, and SSTR2) demonstrated a negative correlation between methylation and gene expression in two sets of paired gastric tumor and normal tissues." (PMID 30510283, 2018).
glaucoma (1 paper, 2021). Increased pressure in the eyeball due to obstruction of the outflow of aqueous humor. "Omidenepag Isopropyl (DE-117) is a selective PTGER2 agonist currently under development for the treatment of glaucoma and ocular hypertension (OHT)." (PMID 34589504, 2021).
Hyperglycemia (1 paper, 2022). An increased concentration of glucose in the blood. "Ptger2 null mice treated with an EP4 agonist showed improvements in glycemia, and were protected from STZ-induced hyperglycemia." (PMID 35448529, 2022).
iron deficiency (1 paper, 2023). "Short-term iron deficiency reduced the PTGER2 level, and FKN was able to increase its expression at both concentrations without the presence of iron." (PMID 37175630, 2023). "In the case of 48 h long iron deficiency, DFO treatment elevated PTGER2 level, and administration of FKN inhibited the effect of DFO." (PMID 37175630, 2023). "Iron deficiency decreased their levels at 24 h, while FKN addition reversed this effect, but later iron deficiency increased PTGER2 and decreased TIMP2, FKN in turn decreased PTGER2 and increased TIMP2 compared to DFO treatments." (PMID 37175630, 2023).
leiomyosarcoma (1 paper, 2022). An uncommon, aggressive malignant smooth muscle neoplasm, usually occurring in post-menopausal women. "Using the SK-UT-1 leiomyosarcoma cells as a human cell line control and NIH-3T3 cells as a murine cell line control, we show that ICR-SS-1 only expressed the human and not the murine version of PTGER2, confirming that this cell line is comprised of a pure population of human cells." (PMID 35954262, 2022).
lung adenocarcinoma (1 paper, 2023). A carcinoma that arises from the lung and is characterized by the presence of malignant glandular epithelial cells. "In human lung adenocarcinoma (TCGA, PanCancer Atlas, 510 patients/samples), CD274 mRNA levels are positively correlated with COX1 (PTGS1), EP2 (PTGER2), EP4 (PTGER4), and DP (PTGDR) with Spearman’s or Pearson’s coefficients over 0.3 and the coefficient of determination (R2) over 0.1." (PMID 37370700, 2023).
lupus nephritis (1 paper, 2025). Glomerulonephritis in the context of systemic lupus erythematosus. "This pharmacological profiling suggests both ALOX5 and PTGER2 represent promising therapeutic targets for further investigation in lupus nephritis." (PMID 40290492, 2025).
myocardial infarction (1 paper, 2023). Gross necrosis of the myocardium, as a result of interruption of the blood supply to the area, as in coronary thrombosis. "A study has identified a haplotype in PTGER2 as related to a minor risk of myocardial infarction." (PMID 36835616, 2023).
pancreatic cancer (1 paper, 2011). "PGE2 may also induces cell migration and invasion by upregulation of matrix metalloproteinase 2 (MMP2) via an ERK-ETS1 cascade in pancreatic cancer cell lines and upregulation of CCR7 via PTGER2 (EP2) and PTGER4 (EP4) in breast cancer cell lines." (PMID 24213116, 2011).
Perthes disease (1 paper, 2023). "Notably, the DEGs identified in the rabbit model of Perthes disease in this study correlated with genes previously reported to be involved in inflammation [IL-6 and HIFa] and angiogenesis [PTGER2 and ALOX12] in Perthes disease." (PMID 37303951, 2023).
polycystic ovary syndrome (1 paper, 2024). A disorder that manifests as multiple cysts on the ovaries. "In a study examining the expression levels of miR-514 and miR-642b, along with their respective candidate target genes, EGFR and PTGER2, in cumulus cells (CCs) from immature and mature oocytes in patients with polycystic ovary syndrome (PCOS), quantitative real-time PCR was employed." (PMID 39684710, 2024).